NBPF26 (NBPF member 26)
Tractability: PROTAC: ubiquitination databases record sites on it.
Gene: Protein-coding gene on chromosome 1 (120,723,945 to 120,842,229, forward strand). Ensembl gene ENSG00000273136.
Subcellular location: Cytoplasm
Subcellular location (Human Protein Atlas): Cytosol; Primary cilium; Cytokinetic bridge; End piece; Golgi apparatus; Microtubules; Mid piece; Principal piece; Vesicles
Gene Ontology:
Molecular function: calcium ion binding
Biological process: animal organ development; positive regulation of signal transduction; system development
Cellular component: cytoplasm; extracellular region
Genetic constraint (gnomAD): Loss-of-function variants: 37 observed, 30.9 expected, observed/expected ratio (o/e) 1.2, 90% interval 0.92 to 1.57. The synonymous counts are far from expectation, so gnomAD's model fits this gene poorly and the ratio says little. Missense variants: 472 observed, 421.47 expected, observed/expected ratio (o/e) 1.12, 90% interval 1.04 to 1.21. Synonymous variants: 192 observed, 151 expected, observed/expected ratio (o/e) 1.27, 90% interval 1.13 to 1.43.
Homologues: Paralogues in human: NBPF14 (82% identical), NBPF10 (82% identical), NBPF12 (68% identical), NBPF19 (67% identical), NBPF20 (66% identical), NBPF9 (55% identical), NBPF8 (54% identical), NBPF1 (49% identical), NBPF11 (47% identical), NBPF15 (39% identical), NBPF3 (29% identical), NBPF4 (18% identical), and 1 more.
Diseases named in the same sentence as NBPF26 in open-access papers:
NBPF26 is named in the same sentence as 1 disease in open-access papers, as found by Europe PMC text mining. Sharing a sentence is not in itself a finding about the gene and the disease.
NBPF26 shares sentences with these, for which no sentence is quoted: tumor (1 paper).